ZMAT1 (zinc finger matrin-type 1)
Synonyms: KIAA1789
Tractability: PROTAC: ubiquitination databases record sites on it.
Gene: Protein-coding gene on chromosome X (101,882,288 to 101,932,090, reverse strand). Ensembl gene ENSG00000166432.
Subcellular location: Nucleus
Subcellular location (Human Protein Atlas): Nucleoplasm
Gene Ontology:
Molecular function: nucleic acid binding; zinc ion binding
Cellular component: nucleus
Homologues: Orthologues: chimpanzee ZMAT1 (99% identical), macaque ZMAT1 (96% identical), pig ZMAT1 (82% identical), dog ZMAT1 (72% identical), rabbit ZMAT1 (69% identical), mouse Zmat1 (57% identical), guinea pig ZMAT1 (55% identical), rat Zmat1 (55% identical), tropical clawed frog krcc1 (28% identical), zebrafish zmat1 (22% identical), Drosophila melanogaster dbf (8% identical), Drosophila melanogaster CG1231 (7% identical). Paralogues in human: KRCC1 (21% identical), ZNF346 (11% identical), ZMAT4 (10% identical), ZNF385B (9% identical), ZNF385C (9% identical), ZNF385D (7% identical), ZNF385A (6% identical), ZMAT3 (5% identical), ZMAT2 (4% identical).
Diseases named in the same sentence as ZMAT1 in open-access papers:
ZMAT1 is named in the same sentence as 11 diseases in open-access papers, as found by Europe PMC text mining. Sharing a sentence is not in itself a finding about the gene and the disease. The quoted sentences say what the papers report.
pancreatic cancer (2 papers, 2022 to 2023). "In the prognostic risk model of this study, ZMAT1 is a low-risk gene for pancreatic cancer, while PRKCI and ZNF185 are high-risk genes for pancreatic cancer." (PMID 37396042, 2023). "Further, we found overexpression of ZMAT1 inhibited pancreatic cancer cell proliferation by inducing p21, leading to impaired S/G2 cell cycle progression." (PMID 35392973, 2022). "Besides, over-expression of ZMAT1 led to decreased pancreatic cancer cell apoptosis." (PMID 35392973, 2022).
pancreatic ductal adenocarcinoma (2 papers, 2022). An infiltrating adenocarcinoma that arises from the epithelial cells of the pancreas. "Zinc finger matrin-type 1 (ZMAT1), a member of the Cys2His2 (C2H2)-type zinc finger family, has been shown to contribute to the anti-cancer effects of SIRT3 in pancreatic ductal adenocarcinoma." (PMID 36497084, 2022).
adrenocortical carcinoma (1 paper, 2022). "Further, patients with low ZMAT1 expression also had poor prognosis in other cancer types including adrenocortical carcinoma, head and neck squamous cell carcinoma, lung adenocarcinoma, mesothelioma, and skin cutaneous melanoma." (PMID 35392973, 2022).
heart failure (1 paper, 2020). Inability of the heart to pump blood at an adequate rate to meet tissue metabolic requirements. "Of these genes, CSDC2, FREM1, and ZMAT1 have never been associated with heart failure." (PMID 33401250, 2020). "Using existing gene expression data in the Gene Expression Omnibus (GEO) database, we screened differentially expressed genes (DEGs) of heart failure and identified six key genes (HMOX2, SERPINA3, LCN6, CSDC2, FREM1, and ZMAT1) by random forest classifier." (PMID 33401250, 2020).
cancer (2 papers, 2022). A tumor composed of atypical neoplastic, often pleomorphic cells that invade other tissues. "ZMAT1 belongs to the C2H2 type zinc finger family, but its biological function is rarely investigated, as well as its role in cancer development." (PMID 35392973, 2022).
tumor (1 paper, 2022). "The established xenograft mouse models suggested that ZMAT1 over-expression significantly inhibited tumor growth." (PMID 35392973, 2022). "Low ZMAT1 expression of PDAC was significantly correlated with poor tumor differentiation (P < 0.05), advanced TNM stage (P < 0.01), high CA19-9 index (P < 0.05), and positive lymph nodes metastasis (P < 0.05)." (PMID 35392973, 2022). "The Transwell assays showed the migration of tumor cells was repressed in the ZMAT1 over-expressed cell line, while silencing of ZMAT1 augmented cellular migration in knock-down cell lines." (PMID 35392973, 2022). "An obvious decrease in tumor weight was observed at the end of the experimental period in the ZMAT1-OV group compared to the control group." (PMID 35392973, 2022). "In addition, RT-qPCR analysis was performed on 25 fresh PDAC tissues and normal pancreas tissues, and the results validated the down-regulation of mRNA levels of ZMAT1 in tumor tissues." (PMID 35392973, 2022). "Thus, ZMAT1 is a tumor suppressor and a vital prognostic biomarker in PDAC and warrants further study in the future." (PMID 35392973, 2022). "Taking these together, our study identified ZMAT1 as a tumor suppressor in PDAC." (PMID 35392973, 2022). "In our study, we demonstrated that ZMAT1 was down-regulated in PDAC and the expression of ZMAT1 was correlated with tumor differentiation, tumor stage, and patient survival, indicating it served as a predictive biomarker for PDAC." (PMID 35392973, 2022). "Furthermore, in vitro and in vivo experiments showed that the over-expression of ZMAT1 suppressed PDAC cells proliferation, migration, and tumor growth." (PMID 35392973, 2022).
ZMAT1 also shares sentences with these, for which no sentence is quoted: head and neck squamous cell carcinoma (1 paper); lung adenocarcinoma (1); mesothelioma (1); osteoporosis (1); skin cutaneous melanoma (1).